INS (insulin)
Diseases named in the same sentence as INS in open-access papers (continued):
Sharing a sentence is not in itself a finding about the gene and the disease.
diabetes (continued). "We also found negative associations with serum insulin in diabetes and albumin (weak correlation each), but HDL-c was not correlated with biochemical parameters." (PMID 35462799, 2022). "We recommend that the INS gene should be screened for mutations in all children diagnosed with diabetes before 12 months of age who are antibody negative." (PMID 35518939, 2022). "The OBs of glargine and detemir were found to be the most unaffordable, whereas the availability of glargine was the highest among the analog insulin in the market, indicating that a vast majority of the patients would have to buy the long-acting insulin to get their diabetes treated." (PMID 35431962, 2022). "Four children (4%) developed diabetes requiring regular insulin treatment at 1 year." (PMID 36053577, 2022). "The significant increase in glucose in the rats exposed to ACR for 10 days (M-ACR group) (this group also had the lowest serum insulin concentration) could suggest the development of insulin dependent diabetes mellitus." (PMID 36050419, 2022). "Due to the high prevalence of prediabetic hyperglycemia and diabetes mellitus (DM) in pancreatic cancer patients (over 75% in high glucose status and 50% in diabetic status), a peripheral increase of insulin level and exogenous insulin injection can often be seen in PDA cases." (PMID 35252207, 2022). "However, a multicenter Brazilian study showed lack of standard protocols in most hospitals, and less than a third of patients with diabetes received adequate insulin therapy." (PMID 35758838, 2022). "For example, adipokines and cytokines may reduce the insulin sensitivity of tissues and lead to the occurrence and development of diabetes." (PMID 36292657, 2022). "The inclusion of 30 min blood glucose level (a good predictor for diabetes occurrence) to determine early insulin secretion helped to understand the combined effect of SCT and ART use on glucose, an observation we would have missed if we had only used fasting and 120 min." (PMID 35167170, 2022). "A key element in the treatment and prevention of diabetes is regular physical activity, which can contribute to a reduction in oxidative stress and the improvement of insulin sensitivity, both of which are processes that play a key role in the pathogenesis of diabetes." (PMID 36555387, 2022). "One study, which tried to predict diabetes progression with baseline LTL in 108 Chinese adults, reported a positive association between adulthood LTL and the Matsuda Index, which provides a measure of whole-body insulin sensitivity." (PMID 36536359, 2022). "Overall, SCFAs could prevent and manage diabetes mellitus via increasing insulin sensitivity, improving glucose homeostasis, and suppressing hepatic gluconeogenesis." (PMID 36140990, 2022). "Therefore, improving insulin sensitivity is an important part of preventing insulin resistance, diabetes, and CVD." (PMID 35185617, 2022). "Similarly, chronic CBD administration improved weight gain, induced anxiolytic effects, decreased hyperglycemia, and increased plasma insulin in a diabetes model." (PMID 36015236, 2022). "Specifically, insulin emerged as an independent risk factor for prevalent and incident CHF, with insulin-treated diabetes portending even worse mortality rates than diabetes alone." (PMID 35574440, 2022). "It has been suggested that smoking impacts body weight and composition, peripheral insulin sensitivity, and pancreatic β cell function, which may be the potential mechanisms behind the relationship between smoking and diabetes." (PMID 35282442, 2022). "The results of this study do not confirm our findings, because carnitine seems to be taken up by muscles and liver, and this process is regulated by insulin and glucagon hormones, while; this study was conducted in subjects with diabetes, whose levels of these hormones are disturbed." (PMID 36704801, 2022).
diabetes (continued). "This suggests that the early onset of MAC may be a more pervasive phenomenon than previously thought in relation to active patients whose diabetes is being managed with non-insulin medication." (PMID 36143268, 2022). "This gene is highly expressed in diabetes, which is characterized by impaired glucose-induced insulin production and its inhibition could reduce glucotoxicity-related β-cell loss." (PMID 35164795, 2022). "In diabetes, the jejunum plays a key role in regulating insulin sensitivity." (PMID 36496564, 2022). "Delivering insulin internationally and globally would be made possible by making it less expensive and its current distribution infrastructure less complicated, which hinders the treatment of the diabetes pandemic in underdeveloped nations." (PMID 36381916, 2022). "Additionally, assessing the insulin effectiveness would require other diabetes-related parameters, such as the 2 h oral glucose tolerance test (11.1 mmol/L) (OGTT) by 2 h plasma glucose (2hPG) and/or haemoglobin A1c (HbA1c)." (PMID 35329071, 2022). "The hypoglycemic mechanism of liraglutide relies on it can increase insulin secretion and alpha beta-cell action to inhibit glucagon release, which leads to decreased plasma glucose in diabetes patients, and the role of central nervous receptors to increase satiety delayed gastric emptying." (PMID 35392872, 2022). "MiR-107 is one of the most promising miRNAs in evaluating diabetes and insulin sensitivity." (PMID 35454146, 2022). "Among those with diabetes, 17% used both “Insulin and non-insulin GLD” in 2009 vs. 23.3% in 2014." (PMID 35701772, 2022). "The traditional clinical diagnostic criteria for MODY (diagnosed <25 years, not insulin treated and a parent affected with diabetes) results in a genetic diagnosis in less than half of cases." (PMID 35445424, 2022). "However, compensatory mechanisms such as increased insulin secretion by the pancreatic beta-cells can delay the development of pre-diabetes." (PMID 36445923, 2022). "An additional question is whether insulin-sensitizing medications may have stronger antidepressant properties in people with IR which may be reversible than in fully developed diabetes." (PMID 36347837, 2022). "Furthermore, INS and IGF1R, predicted targets of KXS in AD therapy, are also associated with diabetes." (PMID 35303280, 2022). "According to modern concepts, the role of adipose tissue in the pathogenesis of diabetes comes down to the accumulation of excess lipids in the liver and to inflammation accompanied by inflammatory cytokine production, leading to impaired insulin signaling." (PMID 35885959, 2022). "Diabetes is described as a group of heterogeneous metabolic diseases characterized by common elements of hyperglycemia and glucose intolerance due to defects in insulin section, impaired effectiveness of insulin or both." (PMID 36139388, 2022). "Increased insulin resistance, once autoimmunity is present, may accelerate the progression to manifest diabetes by increasing the demand on the beta cells for a compensatory rise in insulin secretion." (PMID 35846274, 2022). "Adults with diabetes (primarily insulin-requiring) were referred to remote CDCESs." (PMID 35720451, 2022). "A patient with diabetes should learn how to monitor the symptoms, using a glucometer, administering insulin (pen, insulin pump), using a blood pressure measuring device, performing a urine strip test for ketone bodies and adjusting their menu to daily requirements." (PMID 36141634, 2022). "Identify symptoms of diabetes distress in my patients with insulin-requiring diabetes." (PMID 36589850, 2022). "This could be therefore conceivably hypothesized that higher doses of insulin might result in another renal clearance burden for self-excretion and even it could further compromise the renal function of patients with diabetes." (PMID 36095019, 2022).
diabetes (continued). "Probiotic supplements that contain Bifidobacterium together with Lactobacillus strains may improve insulin sensitivity and reduces fasting levels of plasma glucose in diabetes." (PMID 36614008, 2022). "A previous report had showed that among skeletal muscles, lower limb muscle strength had a greater relation to insulin resistance compared to upper limb, but in this study, we did not examine the relationship between toe grip strength and sarcopenia or diabetes mellitus." (PMID 36280859, 2022). "Thus, PT is an intriguing compound for the treatment of diabetes, and the main aim of the current study was to investigate pterostilbene in relation to the different facets of diabetes, namely insulin resistance and decreased insulin secretion." (PMID 36145121, 2022). "Taken together, increased concentration of insulin precedes diabetes and could be a predictor for type 2 diabetes." (PMID 35757631, 2022). "Arginine plays a vital role in several biological processes, and it has been related to diabetes pathogenesis, where arginine biosynthesis has been found to affect glucose homeostasis, lipolysis, hormone levels, insulin resistance, and fetal programming in the early stages." (PMID 35736441, 2022). "Additionally, genetic factors, obesity, inflammation, oxidative stress, hyperglycemia, hyperinsulinemia, cancer therapies, insulin and some oral hypoglycemic drugs appear to play a role in the crosstalk between diabetes mellitus and cancers." (PMID 35222270, 2022). "The decreased post-ischemic cardiac performance exhibited by heartsfrom late-stage insulin-resistant models of diabetes, may be due to greaterendogenous stores of glycolytic substrates and the resultant excessive productionof lactate and H+." (PMID 39076631, 2022). "Four patients had diabetes mellitus, including two patients who were insulin-dependent." (PMID 35756840, 2022). "We found that in patients with HFpEF and diabetes, sacubitril/valsartan significantly reduced HbA1c compared with valsartan, and that new use of insulin was numerically lower in patients randomized to sacubitril/valsartan than in patients randomized to valsartan." (PMID 35717169, 2022). "Diabetes with reduced/variable penetrance that is rarely treated with insulin." (PMID 35445424, 2022). "Pre-diabetes is a specific clinical condition of cognitive impairment, and physical exercise could promote the benefits of insulin regulation and sensitivity." (PMID 35455914, 2022). "Indeed, under IR and streptozotocin/HFD-induced diabetes, both insulin and irisin have comparable downstream signal pathways in terms of enhancing lipid metabolism, boosting glycogenesis, and decreasing gluconeogenesis." (PMID 35996069, 2022). "Type 2 diabetes mellitus (T2DM) occurs that cannot effectively use the insulin." (PMID 36386219, 2022). "Increasing length of stay for patients in dual, triple or insulin therapies compared to monotherapy may be interpreted in terms of the diabetes’s duration and severity." (PMID 36272025, 2022). "Vitamin B6 may alleviate diabetes by regulating insulin secretion and increasing insulin sensitivity, but its mechanism remains to be explored." (PMID 36355132, 2022). "With an increasing duration of diabetes, the individual may be expecting this phenomenon and take preventive measures such as administering more insulin with any carbohydrates consumed pre-race." (PMID 36992757, 2022). "In contrast, gain-of-function mutations can lead to reduced or absent secretion of insulin, hyperglycemia, and diabetes due to a high degree of K+ efflux and membrane hyperpolarization." (PMID 35954249, 2022). "The average duration of diabetes was 18 years and 77.9% were insulin treated." (PMID 35442990, 2022). "In this study, 420 patients with diabetes using insulin agreed to participate and were interviewed." (PMID 36568796, 2022).
diabetes (continued). "Dysregulated insulin secretion and decreased β-cell mass contribute to the development and progression of diabetes mellitus; therefore, maintaining β-cell physiological function and proper insulin secretion are important for the organismal response to changes in blood glucose." (PMID 36465178, 2022). "Like insulin, polyamines inhibit the diabetes-mediated upregulation of glucose and ketone bodies." (PMID 36613495, 2022). "This may partly be due to those with existing diabetes who were already treated with insulin were those with the most severe diabetes." (PMID 35574035, 2022). "Taken together, although there have been studies evaluating glucagon test and endogenous insulin secretory capacity, to the best of our knowledge, this is the first report to clearly show the relationship between glucagon test and insulin withdrawal in subjects with type 2 diabetes mellitus." (PMID 35574023, 2022). "The treatment of diabetes lies in developing novel functional carriers, which are expected to have the unique capability of monitoring blood glucose levels continuously and dispensing insulin correctly and timely." (PMID 35268787, 2022). "The findings illustrate a therapeutic approach for replacing insulin treatment in diabetes." (PMID 36282594, 2022). "The inclusion of patients with type 1 diabetes might attenuate the prevalence of CAM use since the main treatment for this type of diabetes is insulin." (PMID 36457598, 2022). "This study aimed to determine whether the patterns of diabetic complications differed when patients with type 2 diabetes mellitus (T2DM) were simply classified according to insulin sensitivity and beta-cell function." (PMID 35672344, 2022). "The most prevalent kind of diabetes is type 2 diabetes mellitus, which occurs when there is insulin resistance initially and later the pancreatic beta cells either produce defective insulin or don't produce enough insulin." (PMID 36249664, 2022). "On admission, patients developed ketoacidosis and were started on insulin therapy." (PMID 35769263, 2022). "Starting from the use of insulin, the research progress in improving the pharmacotherapy of diabetes, through the discovery of metformin, sulfonylureas, and thiazolidinediones, failed to reduce cardiovascular events despite the beneficial effects on blood glucose regulation." (PMID 36145112, 2022). "Although ICI-induced diabetes persisted, and required sustained treatment with insulin, this may provide support for single immunotherapy as a new option to maximize the benefits for advanced penile cancer patients." (PMID 36354692, 2022). "In addition, biological pathways related to diabetes were identified, including: insulin section, downstream signaling of insulin and glucagon and sensory perception of chemical stimulus." (PMID 35456489, 2022). "Arachidonic acid is a potent inducer of insulin secretion, while its metabolites contribute differently to insulin resistance and play a crucial part in the onset and progression of prevalent disorders including diabetes and obesity." (PMID 36686454, 2022). "The hypothalamus may play a key role in the early onset of diabetes because it is involved in the control of glucose homeostasis and energy balance, as well as appetite regulation by leptin and insulin." (PMID 36297523, 2022). "Other studies showed that magnesium supplementation improves the insulin resistance index and beta cell function and reduces hemoglobin A1c (HbA1c) levels in patients with type 2 diabetes mellitus (Rodrı ́guez-Mora ́n and Guerrero-Romero, 2003; Guerrero-Romero and Rodrı ́guez-Mora ́n, 2011)." (PMID 36262256, 2022). "The boy was the youngest of six siblings (two males and four females): the older brother had been on insulin therapy since the age of 17, a sister had diabetes since the age of 18, and the other 3 sisters had presented gestational diabetes and were still on oral hypoglycemic therapy." (PMID 36294752, 2022).
diabetes (continued). "In this multicenter retrospective cohort study enrolling incident dialysis patients with diabetes, we showed that patients with severe proteinuria were more likely to have advanced diabetic retinopathy (microangiopathy) and to receive insulin at dialysis initiation." (PMID 35213636, 2022). "During the discharge process, an abundance of information is provided to patients, especially to individuals with a new diagnosis of diabetes or who are new to an insulin regimen, as these patients require self-management of blood glucose, diet, and (potentially) insulin administration." (PMID 36471392, 2022). "Together, these studies suggest that multiple pathways can stimulate downstream signaling, Glut4 translocation, and cellular glucose uptake, thus revealing a complex landscape of insulin resistance mechanisms that may lead to diabetes." (PMID 34801552, 2022). "However, it is unclear if the presence of these insulin-mimic molecules helps to trigger diabetes or protect from diabetes." (PMID 36341463, 2022). "Insulin is produced by pancreatic β cells that is essential especially for the metabolism of carbohydrates and the regulation of glucose levels in the blood and that when insufficiently produced results in diabetes mellitus." (PMID 36033393, 2022). "ORIGIN included 12,537 patients with either prediabetes or diabetes mellitus type 2 and found no increased risk of heart failure with basal insulin compared to placebo (HR 0.90 [95% CI 0.77–1.05])." (PMID 34097240, 2022). "In this direction, a lower basal and early-phase insulin secretion and a lower degree of insulin resistance have been documented in young T2D Japanese individuals with a BMI of 23.4 kg/m2 than in whites with diabetes and a BMI of 27.5 kg/m2." (PMID 36614099, 2022). "Age, diabetes duration, cultural background, family structure, insulin regimen, daily insulin dose, or glycated haemoglobin A1c concentration have not been found to be associated with risk of onset disordered eating in adolescents with type 1 diabetes, but gender and BMI have." (PMID 35978344, 2022). "Diabetes specific aspects (group I = insulin; group O = oral antihyperglycaemic agent)." (PMID 35482748, 2022). "For patients with type 1 or type 2 advanced diabetes, insulin is the cornerstone of therapy." (PMID 35156937, 2022). "In this case, the complicated history of double diabetes was taken through telephonic and online consultations with the help of a nutritionist and diabetes educator, and the treating clinician supervised the insulin doses and frequency." (PMID 36415365, 2022). "In general, physical activity would be effective in patients with diabetes which improves insulin sensitivity, endothelial dysfunction, cellular senescence and interstitial fibrosis which may cause end stage renal damage and renal dysfunction in diabetes." (PMID 36568108, 2022). "In the first period, thematic evolution was observed in 12 research areas: streptozotocin, bone density, type 1 diabetes mellitus, alveolar bone loss, osteoblast, collagen, bone histomorphometry, hyperglycemia, insulin, osteopontin, diabetes mellitus, epidemiology." (PMID 35719662, 2022). "Moreover, exercise can improve insulin sensitivity in both normal and insulin-resistant subjects who have a family history of diabetes." (PMID 36295850, 2022). "Of the participants, 42.65% reported that insulin could treat diabetes, while the majority of students (71.33%) were unaware that long-term insulin use could raise difficulties." (PMID 36466517, 2022). "This is consistent with previous studies that confirmed that body weight (obesity) is one of the most important factors affecting the incidence of diabetes due to the accumulation of fatty tissue in the body, which increases as the cells' resistance to insulin is greater." (PMID 36188660, 2022).